DUXAP9 (double homeobox A pseudogene 9)
Synonyms: FLJ39632; lncRNA-CTD903; LNMAT1; SAN; formerly LINC01296
Gene: Transcribed processed pseudogene on chromosome 14 (19,104,100 to 19,104,713, forward strand). Ensembl gene ENSG00000225210.
Diseases named in the same sentence as DUXAP9 in open-access papers:
DUXAP9 is named in the same sentence as 23 diseases in open-access papers, as found by Europe PMC text mining. Sharing a sentence is not in itself a finding about the gene and the disease. The quoted sentences say what the papers report.
bladder cancer (6 papers, 2017 to 2022). "DUXAP9 has been explored as an oncogene promoting the tumor progression in bladder cancer, thyroid cancer, non‐small cell lung cancer as well as the growth of renal cell carcinoma." (PMID 34168980, 2021).
head and neck squamous cell carcinoma (4 papers, 2021 to 2025). A squamous cell carcinoma that arises from any of the following anatomic sites: lip and oral cavity, nasal cavity, paranasal sinuses, pharynx, larynx, and salivary glands. "Notably, DUXAP9 is upregulated in most cancers, including head and neck squamous cell carcinoma (HNSCC), in the TCGA database." (PMID 37401236, 2023).
lymph node metastasis (4 papers, 2019 to 2023). "A high level of DUXAP9 is positively associated with lymph node metastasis, poor pathological differentiation, advanced clinical stage, worse overall survival, and worse disease‐specific survival in OSCC patients." (PMID 37401236, 2023). "Overexpression of DUXAP9 was frequently observed in moderate/poor pathological grade, advanced clinical stage, lymph node metastasis, worse overall survival (OS), and worse disease‐specific survival (DSS)." (PMID 37401236, 2023).
renal cell carcinoma (4 papers, 2019 to 2022). "The oncogenic potential of DUXAP9 has been explored in various cancers, including thyroid cancer, nonsmall cell lung cancer, bladder cancer, and renal cell carcinoma." (PMID 36614082, 2022). "Functional experiments showed that DUXAP8 and DUXAP9 enhanced but miR-29c-3p weakened growth of renal cell carcinoma." (PMID 31409759, 2019). "These bioinformatic analytic findings indicate that pseudogene DUXAP8 and DUXAP9 may fuel onset and development of renal cell carcinoma by targeting COL1A1 and COL1A2 through competitively binding miR-29c-3p." (PMID 31409759, 2019). "Finally, we detected proliferative roles of DUXAP8, DUXAP9 and miR-29c-3p in renal cell carcinoma cell lines." (PMID 31409759, 2019). "Moreover, functional experiments demonstrated that knockdown of pseudogenes DUXAP8/DUXAP9 reduced proliferative ability of renal cell carcinoma." (PMID 31409759, 2019). "Taken together, miR-29c-3p may be a potential binding miRNA of DUXAP8 and DUXAP9 in renal cell carcinoma." (PMID 31409759, 2019). "Our current results indicated that DUXAP8 and DUXAP9 may act as two key oncogenes in renal cell carcinoma through upregulation of COL1A1 and COL1A2 by competitively binding miR-29c-3p." (PMID 31409759, 2019). "Firstly, we determined the expression levels of five constituents (DUXAP8, DUXAP9, miR-29c-3p, COL1A1 and COL1A2) in 20 pairs of clinical cancer tissues and normal tissues of renal cell carcinoma." (PMID 31409759, 2019). "All these findings suggest that pseudogene DUXAP8/DUXAP9-miR-29c-3p-COL1A1/COL1A2 may be a critical signaling pathway in onset and progression of renal cell carcinoma." (PMID 31409759, 2019). "Taken together, amplification of pseudogenes DUXAP8 and DUXAP9 may lead to increase expression of COL1A1 and COL1A2 by competitively binding to miR-29c-3p, resulting in uncontrolled cell proliferation in renal cell carcinoma." (PMID 31409759, 2019).
oral squamous cell carcinoma (3 papers, 2021 to 2023). "The authors identify a lncRNA DUXAP9 is highly correlated with poor clinicopathological features in oral squamous cell carcinoma (OSCC) patients." (PMID 37401236, 2023).
renal carcinoma (3 papers, 2021 to 2023). A carcinoma arising from the epithelium of the renal parenchyma or the renal pelvis. "We further explored the effect of DUXAP9 on RCC in migration and invasion, as our results showed that high DUXAP9 expression was significantly associated with poor PFS in patients with renal cancer cells." (PMID 34168980, 2021). "To clarify the molecular mechanism underlying the pro-tumor effects of DUXAP9 in renal cancer cells, we did a bioinformatics analysis." (PMID 34168980, 2021). "Tan and his colleagues found that N6-methyladenosine modification of lncRNA DUXAP9 promoted renal cancer cell proliferation migration and invasion by boosting the PI3K/AKT signaling." (PMID 36825082, 2023). "The regulation of Snail, a transcriptional repressor of epithelial genes by DUXAP9 was shown to promote EMT in renal cancer cells." (PMID 36614082, 2022). "The results of one of the studies indicate that DUXAP9 knockdown diminished the activation of Akt signalling in renal cancer cells." (PMID 36614082, 2022). "This study provides a more detailed understanding of DUXAP9 as a new potential target for the diagnosis and treatment of renal cancer." (PMID 34168980, 2021). "In this study, using western blotting and in vitro (cell line) assays, we showed that DUXAP9 is an important regulator of Snail and promotes the invasion and migration in renal cancer cells." (PMID 34168980, 2021). "Meanwhile, we next evaluated that management of LY294002 in renal cancer cells also impaired the advancement of tumor cells growth of DUXAP9-overexpression cells through CCK-8 assays and colony formation assays." (PMID 34168980, 2021). "This is consistent with our findings that DUXAP9 knockdown reduced the activation of Akt signaling in renal cancer cells." (PMID 34168980, 2021). "A classical m6A motif (GAACT) was found in the DUXAP9 sequence using SRAMP (an m6A modification site predictor), so we wondered whether DUXAP9 exhibited m6A modification, which could maintain its fate in renal cancer cells." (PMID 34168980, 2021). "DUXAP9 knockdown in renal cancer cells inhibited renal cancer cells proliferation and motility capacities in vitro and reversed epithelial–mesenchymal transition (EMT), whereas overexpression of DUXAP9 promoted renal cancer cells proliferation and motility capacities in vitro and induced EMT." (PMID 34168980, 2021). "To further validate this hypothesis, we used LY294002 to inhibit PI3K, which abrogated the tumorigenic effects of DUXAP9 in renal cancer cells." (PMID 34168980, 2021). "Further, mechanistic studies showed that m6A modification of DUXAP9 allows it to exert its function by activating the PI3K/Akt signaling pathway and Snail expression in renal cancer cells." (PMID 34168980, 2021). "The data confirmed that DUXAP9 is an important mediator in the Akt regulatory network, activating PI3K to induce Akt/mTOR signaling in renal cancer cells." (PMID 34168980, 2021). "DUXAP9 promoted proliferation and motility capacities, suppressed apoptosis, and promoted EMT in renal cancer cells." (PMID 34168980, 2021). "DUXAP9 knockdown decreased Snail expression and inhibited EMT progression, while DUXAP9 overexpression activated Snail-induced EMT signaling in renal cancer cells." (PMID 34168980, 2021). "DUXAP9 activate PI3K/AKT pathway and Snail expression in renal cancer cells." (PMID 34168980, 2021). "Furthermore, we clarified that the stability of DUXAP9 was regulated by m6A modification, and DUXAP9 activated PI3K/Akt signaling pathway and Snail expression in renal cancer cells." (PMID 34168980, 2021).
non-small cell lung carcinoma (2 papers, 2019 to 2021). A group of at least three distinct histological types of lung cancer, including non-small cell squamous cell carcinoma, adenocarcinoma, and large cell carcinoma. "DUXAP9 has also been found to promote non-small-cell lung cancer progression by directly binding with Cbl-b and thus augmenting EGFR signaling." (PMID 31409759, 2019).
breast tumors (1 paper, 2022). "For example, events in CYB561 and CEACAM1 are enriched in HER2+, and E2F4, AP2A2, MGAT4B, and DUXAP9 events are enriched in basal-like breast tumors." (PMID 35044822, 2022).
kidney cancer (1 paper, 2019). Primary or metastatic malignant neoplasm involving the kidney. "Higher expression of DUXAP8 and DUXAP9 indicated poorer prognosis of kidney cancer." (PMID 31409759, 2019). "Moreover, our results suggested that DUXAP8 and DUXAP9 and other components in this pathway possessed significant prognostic values in patients with kidney cancer." (PMID 31409759, 2019).
cancer (14 papers, 2014 to 2025). A tumor composed of atypical neoplastic, often pleomorphic cells that invade other tissues. "It is generally appreciated that the activation of oncogenic transcription factors (TFs) contributes to the aberrant expression of lncRNAs in cancer, and hence, we searched for transcription factors that potentially regulate the upregulation of DUXAP9 in OSCC." (PMID 37401236, 2023). "To verify DUXAP9 expression in cancer, we performed a pancancer analysis that compared tumor tissues and paracancerous tissues using The Cancer Genome Atlas (TCGA) database." (PMID 37401236, 2023). "Two pseudogenes DUXAP8 and DUXAP9 were significantly upregulated in cancer samples compared with normal samples." (PMID 31409759, 2019). "Expression of DUXAP8, DUXAP9, COL1A1 and COL1A2 were significantly increased in cancer samples compared to normal controls while miR-29c-3p expression was decreased." (PMID 31409759, 2019). "qPCR showed that DUXAP8, DUXAP9, COL1A1 and COL1A2 were significantly upregulated in renal cell carcinoma cancer samples compared with normal controls whereas miR-29c-3p expression in cancer tissues was decreased." (PMID 31409759, 2019).
tumor (14 papers, 2017 to 2025). "The mice injected with DUXAP9‐overexpressing reporter cells form more tumor nodules in their lungs than the mice injected with vector cells." (PMID 37401236, 2023). "The knockdown of DUXAP9 significantly reduced tumor volumes and weights in the knockdown group compared with the control group." (PMID 37401236, 2023). "The expression of DUXAP9 is also higher in genotype‐tissue expressed (GTEx) OSCC tumor samples from TCGA than in their corresponding paracancerous controls." (PMID 37401236, 2023). "The results showed a consistent tendency for DUXAP9 expression to be increased in ccRCC tissues compared to adjacent non-tumor tissues (P<0.001)." (PMID 34168980, 2021). "And DUXAP9 involved with activity of PI3K/Akt/GSK3β/Snail pathway in ccRCC tumor tissues need further verification." (PMID 34168980, 2021). "In the present study, our results made a more particular knowledge of that lncRNA DUXAP9 is an extremely important factor in promoting the tumor progression of localized ccRCC." (PMID 34168980, 2021). "We first examined DUXAP9 expression in 112 pairs of primary localized ccRCC and adjacent non-tumor tissues from SYSUCC Biobank." (PMID 34168980, 2021). "In this study, we characterized a lncRNA DUXAP9 and the upregulation of DUXAP9 was analyzed by quantitative real-time PCR in 112 pairs of localized ccRCC tumor tissues compared with adjacent normal tissues." (PMID 34168980, 2021). "In situ hybridization (ISH) analysis using a specific probe revealed that the expression levels of DUXAP9‐206 were significantly elevated in NSCLC tumour tissues compared with paired adjacent non‐tumour tissues." (PMID 30515972, 2019). "Using an experimental mouse xenograft model, we found that DUXAP9‐206‐transduced cells showed faster tumour growth rates than vector‐control cells." (PMID 30515972, 2019). "They concluded that Lnc-DUXAP9 might promote tumour proliferation via IGF2BP2/Lnc-DUXAP9/PI3K/Akt axis." (PMID 37284313, 2023). "The RNAscope assay also showed that DUXAP9 is enriched in OSCC tumor tissues." (PMID 37401236, 2023). "To test DUXAP9 expression in the regulation of tumorigenesis in vivo, we subcutaneously injected DUXAP9 knockdown OSCC cells into null mice and monitored tumor formation for 3 weeks." (PMID 37401236, 2023). "We explored whether DUXAP9 is involved in Akt-induced EMT, tumor growth, and invasiveness." (PMID 34168980, 2021).
DUXAP9 also shares sentences with these, for which no sentence is quoted: osteosarcoma (3 papers); hepatocellular carcinoma (2); pancreatic ductal adenocarcinoma (2); bladder tumors (1); cholangiocarcinoma (1); esophageal squamous cell carcinoma (1); gastric cancer (1); melanoma (1); Oral leukoplakia (1); ovarian carcinoma (1); stomach adenocarcinoma (1); thyroid cancer (1).